MIR519C (microRNA 519c)
Synonyms: hsa-mir-519c; MIRN519C; mir-519c
Gene: MicroRNA gene on chromosome 19 (53,686,469 to 53,686,555, forward strand). Ensembl gene ENSG00000207788.
Gene Ontology:
Biological process: miRNA-mediated post-transcriptional gene silencing
Homologues: Orthologues: chimpanzee ptr-mir-519c (100% identical), macaque mml-mir-519c (94% identical). Paralogues in human: MIR519A2 (91% identical), MIR516A1 (90% identical), MIR520C (90% identical), MIR516A2 (89% identical), MIR518F (89% identical), MIR520F (89% identical), MIR519B (87% identical), MIR522 (87% identical), MIR523 (87% identical), MIR516B1 (86% identical), MIR518C (86% identical), MIR518E (86% identical), and 12 more.